PAX3 (paired box 3)
Description:
Transcription factor that may regulate cell proliferation, migration and apoptosis. Involved in neural development and myogenesis. Transcriptional activator of MITF, acting synergistically with SOX10.
Synonyms: HUP2; PAX-3; CDHS; WS1; WS3
Tractability: No criterion of Open Targets' tractability assessment is met for any kind of drug.
Gene: Protein-coding gene on chromosome 2 (222,199,887 to 222,298,998, reverse strand). Ensembl gene ENSG00000135903.
Subcellular location: Nucleus
Subcellular location (Human Protein Atlas): Nucleoplasm
Pathways (Reactome):
Developmental Biology: Specification of the neural plate border; Transcriptional and post-translational regulation of MITF-M expression and activity
Chromatin organization: HATs acetylate histones
Gene Ontology:
Molecular function: protein binding; sequence-specific DNA binding; sequence-specific double-stranded DNA binding; DNA-binding transcription factor activity; DNA-binding transcription factor activity, RNA polymerase II-specific; RNA polymerase II cis-regulatory region sequence-specific DNA binding; DNA binding
Biological process: positive regulation of DNA-templated transcription; positive regulation of transcription by RNA polymerase II; animal organ morphogenesis; apoptotic process; nervous system development; regulation of transcription by RNA polymerase II; sensory perception of sound; anatomical structure morphogenesis; regulation of DNA-templated transcription
Cellular component: nucleoplasm; nucleus; chromatin
Genetic constraint (gnomAD): Loss-of-function variants: 14 observed, 53.5 expected, observed/expected ratio (o/e) 0.26, 90% interval 0.17 to 0.41. The upper end of that interval is the gene's LOEUF score, 0.41, which puts it in group 1 of 6, group 1 being the genes least tolerant of losing a copy. Missense variants: 540 observed, 667.46 expected, observed/expected ratio (o/e) 0.81, 90% interval 0.75 to 0.87. Synonymous variants: 280 observed, 267.83 expected, observed/expected ratio (o/e) 1.05, 90% interval 0.95 to 1.15.
Gene-disease validity (ClinGen):
ClinGen rates the evidence that PAX3 causes each of these diseases.
Waardenburg syndrome (autosomal dominant): Definitive. A disorder characterized by varying degrees of deafness and minor defects in structures arising from neural crest, including pigmentation anomalies of eyes, hair, and skin.
Cancer hallmarks: escaping programmed cell death (promotes); invasion and metastasis (promotes); proliferative signalling (promotes); suppression of growth (promotes)
Homologues: Orthologues: chimpanzee PAX3 (100% identical), macaque PAX3 (100% identical), rabbit PAX3 (99% identical), guinea pig PAX3 (99% identical), pig PAX3 (99% identical), dog PAX3 (99% identical), mouse Pax3 (99% identical), rat Pax3 (94% identical), tropical clawed frog pax3 (93% identical), zebrafish pax3a (77% identical), zebrafish pax3b (67% identical). Paralogues in human: PAX7 (76% identical), PAX5 (33% identical), PAX2 (31% identical), PAX8 (30% identical), PAX1 (27% identical), PAX4 (26% identical), PAX9 (25% identical), PAX6 (19% identical), ARX (18% identical), PITX2 (17% identical), ALX4 (16% identical), NOBOX (16% identical), and 38 more.
Diseases named in the same sentence as PAX3 in open-access papers:
PAX3 is named in the same sentence as 164 diseases in open-access papers, as found by Europe PMC text mining. Sharing a sentence is not in itself a finding about the gene and the disease. The quoted sentences say what the papers report.
rhabdomyosarcoma (142 papers, 2001 to 2026). A rare aggressive malignant mesenchymal neoplasm arising from skeletal muscle. "PAX3/7-FOXO1-driven rhabdomyosarcomas are rarely associated with therapeutically actionable genetic aberrations." (PMID 35879366, 2022). "Rhabdomyosarcoma (RMS) is a pediatric malignancy of skeletal muscle lineage with an aggressive subtype caused by translocations involving PAX3- /PAX7-FOXO1 chimeric transcription factors." (PMID 34836971, 2021). "Chromosomal translocations causing gene fusions between FKHR (Foxo1) and Pax3 or Pax7 are characteristic of alveolar rhabdomyosarcoma (ARMS), a pediatric soft tissue cancer derived from the muscle lineage." (PMID 33193700, 2020). "Alveolar rhabdomyosarcoma is a pediatric soft-tissue sarcoma caused by PAX3/7-FOXO1 fusion oncogenes and is characterized by impaired skeletal muscle development." (PMID 29869612, 2018). "Distinct gene expression signatures are associated with PAX3-FKHR or PAX7-FKHR gene fusions in rhabdomyosarcomas and determine the prognosis in this cancer." (PMID 27649156, 2016). "Mutations in PAX3 are associated with Waardenburg syndrome, craniofacial-deafness-hand syndrome, and alveolar rhabdomyosarcoma." (PMID 27034728, 2016). "For example it has been shown previously that mouse mesenchymal stem cells expressing PAX3-FKHR fusion gene form alveolar rhabdomyosarcomas by cooperating with secondary mutations." (PMID 26384300, 2015). "The alveolar rhabdomyosarcoma is characterized by the chromosomal translocation that fuses the PAX3 or PAX7 genes with the gene encoding the transcription factor FOXO1/FKHR." (PMID 25341037, 2014). "Alveolar rhabdomyosarcoma (aRMS) is a myogenic childhood sarcoma frequently associated with a translocation-mediated fusion gene, Pax3:Foxo1a." (PMID 24274149, 2013). "Translocation of this gene with PAX3 has been associated with alveolar rhabdomyosarcoma (RefSeq, NCBI)." (PMID 20485516, 2010). "As the transcriptome analysis show that the MAPK signalling pathway is down-regulated due to loss of pax3 genes, we intended to determine whether Pax3 is involved in rhabdomyosarcoma formation and progression in zebrafish." (PMID 36229514, 2022). "Thus, the identification of new therapeutic strategies for high-risk PAX3/7-FOXO1-expressing rhabdomyosarcoma remains urgent but challenging." (PMID 35879366, 2022). "The transcription factor paired box 3 (Pax3) regulates muscle development, and its gain-of-function mutation, Pax3FKHR, causes aberrant expression of its target genes and is associated with a severe form of alveolar rhabdomyosarcoma." (PMID 35682605, 2022). "Although PAX3 mutations are more usually associated with Waardenburg syndrome and as a cause of neural tube defects, craniofacial-deafness-hand syndrome, alveolar rhabdomyosarcoma, and congenital hearing loss, there is a low prevalence of hydrocephalus reported within PAX3 mutant patients." (PMID 26949601, 2016). "Given our findings, we believe that targeting FGFR4 will be most effective in ERMS with high expression (due to amplification) or mutation of FGFR4 or in alveolar rhabdomyosarcoma (ARMS) where the PAX3/7-FOXO1 fusion gene found in ARMS directly increases expression of FGFR4." (PMID 24124571, 2013). "Rb1 loss from an already low pRb baseline is a significant disease modifier, raising the possibility that some cases of pleomorphic rhabdomyosarcoma may in fact be Pax3:Foxo1a-expressing aRMS with Rb1 or pRb loss of function." (PMID 24274149, 2013).
rhabdomyosarcoma (continued). "It is not unprecedented that the number of binding sites for a particular factor is far greater than the number of genes that are differentially expressed when that factor is induced, as was the case with the myogenesis regulator MyoD, or the PAX3-FKHR fusion associated with rhabdomyosarcoma." (PMID 22594313, 2012). "Alveolar rhabdomyosarcoma (aRMS) is a pediatric soft tissue cancer commonly associated with a chromosomal translocation that leads to the expression of a Pax3:Foxo1 or Pax7:Foxo1 fusion protein, the developmental underpinnings of which may give clues to its therapeutic approaches." (PMID 28883017, 2017). "Fusion-positive rhabdomyosarcoma (FP-RMS) arises from at least seven distinct oncofusions sharing a common PAX3/7 N-terminal DNA-binding domain fused to divergent C-terminal partners." (PMID 42209514, 2026). "The fact that the driver PAX3 fusion of BSNS overlaps with that of other tumors, e.g., alveolar rhabdomyosarcoma, further complicates this diagnostic dilemma." (PMID 42183964, 2026). "PAX3::FOXO1 fusion gene is detected in 85% of alveolar rhabdomyosarcoma, while PAX7::FOXO1 fusion gene is seen in 10%." (PMID 40666501, 2025). "In alveolar rhabdomyosarcoma cells, the PAX3::FOXO1 fusion transcript has been demonstrated to suppress Hippo signalling through Ras associated domain family 4 (RASSF4) which modulates the activity of the MST1 kinase, leading to overexpression of YAP." (PMID 40983796, 2025). "Our assay reported several diagnostic fusions, including PAX3 and PAX7 joining with FOXO1 in alveolar rhabdomyosarcoma and SS18-SSX fusion in synovial sarcomas." (PMID 40711866, 2025). "Our laboratory has previously demonstrated that alveolar rhabdomyosarcoma (ARMS) driven by the PAX3::FOXO1 (P3F) oncofusion protein can arise when P3F is expressed in endothelial progenitors in mice." (PMID 41252925, 2025). "The strong causal relationship between PAX3/7–FOXO1 fusion oncoproteins and alveolar rhabdomyosarcoma provides the rationale to employ therapeutic approaches targeting these fusion proteins." (PMID 40563544, 2025). "Alveolar rhabdomyosarcoma (ARMS) is a highly aggressive pediatric soft-tissue sarcoma driven by PAX3/7-FOXO1 fusion proteins." (PMID 40508013, 2025). "In fusion-positive rhabdomyosarcoma, the DNA-binding capabilities of PAX3 or PAX7 are fused with the transcriptional activating domain of FOXO1." (PMID 40983796, 2025). "Common diagnostic examples include Ewing sarcoma with the characteristic EWSR1-FLI1 fusion, alveolar rhabdomyosarcoma distinguished from other rhabdomyosarcomas by the PAX3/7-FOXO1 fusion, and synovial sarcoma with its pathognomonic SS18-SSX1/2/4 fusion." (PMID 40227789, 2025). "Alveolar rhabdomyosarcoma (ARMS) is an aggressive soft tissue sarcoma typically driven by the oncofusion protein PAX3::FOXO1 (P3F)." (PMID 41252925, 2025). "As previously discussed, examples such as miR-217 suppressing the carcinogenic IL-6 gene in cardiac myxoma and miR-1 inhibiting c-Met and PAX3 to suppress tumor growth in rhabdomyosarcoma showcase the diverse roles of miRNAs in different tumors." (PMID 38826780, 2024). "Alveolar rhabdomyosarcoma is a sarcoma characterized by the expression of the paired box 3-forkhead box protein O1 (PAX3-FOXO1) fusion oncogene." (PMID 39791714, 2024). "For example, alveolar rhabdomyosarcoma is characterized by consistent chromosomal translocations and chimeric genes, PAX3-FKHR and PAX7-FKHR, which are expressed as novel fusion transcripts." (PMID 38520005, 2024). "In the case of PAX3::FOXO1-driven rhabdomyosarcoma, inhibition of the RAS-ERK pathway leads to myogenic differentiation, similarly to normal muscle precursor cells." (PMID 38611033, 2024). "This can directly determine how the fusion executes its oncogenic function: for example, PAX3::FOXO1 (fusion-positive rhabdomyosarcoma) binds DNA at sites determined by the PAX3 DNA-binding domains, whereas FOXO1 provides transactivating capacity." (PMID 39530749, 2024).
rhabdomyosarcoma (continued). "Fusions of PAX3 and −7 are the drivers of both alveolar rhabdomyosarcoma (aRMS) and biphenotypic sinonasal sarcoma (SNS)." (PMID 38611033, 2024). "SAHA, a histone deacetylase inhibitor, and fenretinide, a vitamin A analog, have also been shown to reduce PAX3::FOXO1 protein levels in rhabdomyosarcoma cells." (PMID 38473380, 2024). "It has been reported that PAX3-Foxo1 can inhibit miR-221 and contribute to the pathogenesis of alveolar rhabdomyosarcoma, suggesting that Prx II regulates the expression of miR-221 through Foxo1." (PMID 37864270, 2023). "In rhabdomyosarcoma, the fusion gene between PAX3 or PAX7 and FOXO1 is an important characteristic within the alveolar subtype." (PMID 37152023, 2023). "Other examples include rhabdomyosarcoma cells resistant to PAX3 or both PAX3 and MYOD1 KO that had an enhanced dependency on MYC compared to lineage sensitive lines." (PMID 37554444, 2023). "Translocations between 2q35 and 13q14 resulting in interaction of the FOXO1 enhancer B116Z with the Pax3 promoter have been observed in rhabdomyosarcoma cell lines." (PMID 37426677, 2023). "The PAX3-FOXO1 fusion protein arises from a commonly observed genetic abnormality of alveolar rhabdomyosarcoma (aRMS) that results from the fusion of the DBD of PAX3 and the TAD of FOXO1." (PMID 37174744, 2023). "Certain subtypes are strongly associated with genetic fusions, such as Ewing’s sarcoma (EWSR1::FLI1), alveolar rhabdomyosarcoma (PAX3/7::FOXO1), and synovial sarcoma (SS18::SSX1/2/4)." (PMID 36980578, 2023). "FOXO1, also known as Forkhead Homologue in Rhabdomyosarcoma (FKHR), was initially identified as a fusion protein with Pax3 in alveolar rhabdomyosarcoma." (PMID 35406686, 2022). "Rhabdomyosarcomas expressing PAX3/7-FOXO1 have a high metastatic potential and are often refractory to chemotherapy." (PMID 35879366, 2022). "Overexpression of miR-29 and 206 downregulates cell cycle gene expression and induces cell cycle arrest through stabilization of PAX3 in rhabdomyosarcoma, suggesting a tumor suppressor role for PAX3." (PMID 33817318, 2021). "PAX3/FOXO1 fusion accelerated PAX3/FOXO1-positive alveolar rhabdomyosarcoma aggregation by regulating PPP2R1A." (PMID 33817318, 2021). "Rhabdomyosarcoma, a common soft‐tissue malignancy, resulted from overexpression of Pax3/7‐FOXO1 fusion gene." (PMID 33336498, 2021). "PAX3 was the 5′ fusion partner in 29 cases with 3′ partners being FOXO1 fusions identified in alveolar rhabdomyosarcoma cases, MAML3 and NCOA1 fusions in two different biphenotypic sinonasal sarcoma cases." (PMID 34745213, 2021). "In the PLAGL1:FOXO1 fusion observed here, the DNA binding domain of PLAGL1 is juxtaposed to the C-terminal TAD of FOXO1, which seems quite similar to PAX3:FOXO1 rearrangements as frequently observed in alveolar rhabdomyosarcoma." (PMID 34355256, 2021). "Accordingly, thapsigargin treatment suppresses the growth of Pax3-FoxO1 expressing alveolar rhabdomyosarcoma cell lines and xenografts." (PMID 34195082, 2021). "The role of PAX3 as an oncogene has been widely reported in various cancers, such as neuroblastoma, glioblastoma, melanoma, Ewing sarcoma, rhabdomyosarcoma, and gastric cancer." (PMID 31823759, 2019). "Here, we describe the employment of phospho-protein arrays in the profiling of cell signaling pathways in four serial tumor samples taken from a child suffering from PAX3/FKHR-positive alveolar rhabdomyosarcoma of the ala of nose." (PMID 31616636, 2019). "Other proteomic studies have recently been carried out for soft tissue sarcomas with specific fusion genes such as EWS/FLI1 (for Ewing sarcomas) and PAX3/FOXO1 (for alveolar rhabdomyosarcoma)." (PMID 30680066, 2018). "Sarcoma-specific fusion gene transcripts like EWSR1-ERG or EWSR1-FLI1 in EWS or PAX3-FKHR or PAX7-FKHR in alveolar rhabdomyosarcoma (aRMS) are providing a promising way to detect CTCs." (PMID 30326929, 2018).
rhabdomyosarcoma (continued). "The chromosomal translocation that leads to alveolar rhabdomyosarcoma development generates a novel TAD that is likely to favour ectopic PAX3:FOXO1 oncogene activation in non-PAX3 territories." (PMID 28615069, 2017). "The PAX3/7-FOXO1 fusion oncoprotein is thought to be the initiating tumor promoting insult in fusion-positive rhabdomyosarcoma." (PMID 27853183, 2016). "Alveolar rhabdomyosarcoma, a muscle tumor in children, is typified by a translocation that fuses the PAX3 gene on chromosome 2 to the FOXO1 gene on chromosome 13." (PMID 25659124, 2015). "PAX3-FOXO1 (PAX3-FKHR) is the fusion protein produced by the genomic translocation that characterizes the alveolar subtype of Rhabdomyosarcoma, a pediatric sarcoma with myogenic phenotype." (PMID 25806826, 2015). "The alveolar subtype of rhabdomyosarcoma (ARMS) is typically characterized by a specific reciprocal chromosomal translocation involving the PAX3 and FKHR or PAX7 and FKHR genes, respectively." (PMID 26587222, 2015). "The FOXO1 gene was particularly interesting since it is fused to either the PAX3 gene or the PAX7 gene in alveolar rhabdomyosarcoma." (PMID 25341037, 2014). "In our studies, we sought to refine experimentally the range of possibilities for the cell of origin of Pax3:Foxo1+ rhabdomyosarcoma." (PMID 25030697, 2014). "Biomarkers in use from these pathways include FOXO1 within the VEGF pathway, as a prognostic marker in rhabdomyosarcoma (as a fusion gene with PAX3) and also shown to be highly expressed in the infancy cluster of increased gene expression." (PMID 23941278, 2013). "PAX3 and PAX7 are implicated in Alveolar Rhabdomyosarcoma (ARMS), a pediatric tumour of skeletal muscle origin that results from a translocation between PAX3/7 and FKHR (FOXO1A)." (PMID 23650549, 2013). "In order to generate a more robust alveolar rhabdomyosarcoma model, mice specifically expressing a Pax3-Fkhr transgene in the muscle under the influence of Myf6-Cre-mediated activation were generated." (PMID 23036318, 2012). "PAX3 (paired box protein Pax-3) and PAX6 (paired box protein Pax-6) are nuclear transcription factors involved in the development of many tissues and the role of PAX3 in rhabdomyosarcoma and malignant melanoma is discussed." (PMID 23213280, 2012). "In this setting, only alveolar rhabdomyosarcoma can be reliably diagnosed by molecular test for PAX3 or 7-FKHR translocation." (PMID 21762516, 2011). "Of great interest, a miRNA signature was identified in rhabdomyosarcoma tumours from patients in accordance with the molecular translocation Pax3 or Pax7." (PMID 21437224, 2011). "In such case, diagnosis of de novo rhabdomyosarcoma is basically a function of extensiveness of tissue sampling except for alveolar rhabdomyosarcoma for which molecular analysis for PAX3/7-FHKR translocation can be used to confirm the diagnosis." (PMID 21762516, 2011). "In rhabdomyosarcoma, the fusion protein PAX3-FKHR directly interacts with Stat3 and changes gene expression profiles that are normally regulated by JAK/STAT signaling pathways." (PMID 17598902, 2007). "Vaccination trials of fusion gene-derived peptides have been reported with BCR-ABL in 12 patients with chronic myelogenous leukemia, EWS-FLI1 in 12 patients with Ewing's sarcoma, and PAX3-FKHR in four patients with alveolar rhabdomyosarcoma." (PMID 15647119, 2005). "Indeed, PAX3 is overexpressed in several cancers, including melanoma, neuroblastoma, and rhabdomyosarcoma." (PMID 41897383, 2026).